TRAJ20 (T cell receptor alpha joining 20)
Gene: T-cell receptor joining (J) gene on chromosome 14 (22,524,325 to 22,524,381, forward strand). Ensembl gene ENSG00000211869.
Diseases named in the same sentence as TRAJ20 in open-access papers:
TRAJ20 is named in the same sentence as 1 disease in open-access papers, as found by Europe PMC text mining. Sharing a sentence is not in itself a finding about the gene and the disease. The quoted sentences say what the papers report.
cancer (2 papers, 2020 to 2025). A tumor composed of atypical neoplastic, often pleomorphic cells that invade other tissues. "Of the remaining cancer-activated MR1-restricted TCRs, some used the MAIT cell–preferred TRAJ20 and TRAJ12 to generate a similarly placed tyrosine and others used TRAJ26, TRAJ47, or TRAJ32 to encode this tyrosine residue." (PMID 39744940, 2025). "Within all the three tissue compartments examined for each of the three cancer types, TRAJ33 was the most commonly used Jα segment whereas TRAJ12 and TRAJ20 were detectable only in a minority of MAIT cells." (PMID 32849590, 2020).